GATA2 (GATA binding protein 2)
Diseases named in the same sentence as GATA2 in open-access papers (continued):
Sharing a sentence is not in itself a finding about the gene and the disease.
breast carcinoma (24 papers, 2012 to 2025). "Upregulated GATA2 expression has been implicated in several tumour types, such as breast cancer, colorectal cancer and liver cancer." (PMID 35488350, 2022). "It indicates that the doxorubicin induces the dysregulation of hiPSC-CMs derived RAD9A, HSPA1B, GATA2, IGF2R, CD200, ERCC8, and BCL11A genes that are associated with the pathogenesis of doxorubicin-induced cardiotoxicity in breast cancer patients." (PMID 37684436, 2023). "The transcription factor GATA2 is overexpressed in human breast carcinomas and promotes BC cell growth." (PMID 37893423, 2023). "GATA2 was discovered to be a significant epigenetic regulator for G9a in breast cancer, which affects breast cancer cell survival and carcinogenesis." (PMID 37684436, 2023). "Overexpression of GATA2 correlates with development of breast cancer by negatively regulating the transcription of phosphatase and tensin homologue (PTEN)." (PMID 35326649, 2022). "The GATA2 TF is related to kidney and breast cancer-related pathway when the higher expression pattern of YY1 TFs increases the tumour size and higher TNM stage." (PMID 36016137, 2022). "These traits associated with invasiveness and metastasis in many cancers have been recently linked to increased GATA2 as well as GATA3 expression after induced hypomethylation by hypoxia or hypomethylating agents in ovarian and breast cancer." (PMID 34831278, 2021). "In breast cancer, GATA2 was found to be a key epigenetic regulator for G9a, which impacts breast cancer cell survival and tumorigenesis." (PMID 30872657, 2019). "In breast cancer, GATA2 promotes cell proliferation and stimulates AKT phosphorylation by inhibiting PTEN transcription." (PMID 26287967, 2015). "In the gene regulatory network by using the NetworkAnalyst web server, we found five (two from Encode and three from Jasper such as FOXC1, GATA2, FOXL1, ZNF24 and NR2F6) potential Transcription Factors (TFs) and all of those are linked with several cancer including breast cancer." (PMID 38717954, 2024). "Of the transcriptional regulators, GATA2, PHF1 and SIN3A were previously reported to be involved in breast cancer." (PMID 30375428, 2018). "Overexpression of GATA-2 was detected in a subset of human chronic myelogenous leukemia and human neuroblastoma samples, while GATA-3 was shown to be highly expressed in breast cancer, lymphoma and other tumors." (PMID 27528231, 2016). "Finally, we validated the expression level of immune-related genes in breast cancer patients-derived cardiomyocytes with doxorubicin-induced cardiotoxicity and found that the level of RAD9A, HSPA1B, GATA2, IGF2R, CD200, ERCC8, and BCL11A genes are consistently dysregulated." (PMID 37684436, 2023). "Finally, we validated that RAD9A, HSPA1B, GATA2, IGF2R, CD200, ERCC8, and BCL11A genes are consistently dysregulated in the doxorubicin-induced human-induced pluripotent stem cell-derived cardiomyocytes (hiPSC-CMs) derived from breast cancer patients." (PMID 37684436, 2023). "In addition, high GATA2 expression in non-cultured human breast carcinomas promotes the proliferation of breast cancer cells by inhibiting the transcription of PTEN." (PMID 26287967, 2015). "In addition, we found that there was a significant negative correlation between GATA2 and miR-1304-3p in African American breast cancer patients (spearman R = -0.27, p = 0.001), while there was only a minor correlation in Caucasian American patients (spearman r = -0.097, p = 0.0345)." (PMID 36517516, 2022). "However, there is no report on the role of GATA2 in prognosis in breast cancer." (PMID 30872657, 2019). "Plasmids containing ERE3 and ERE4 were then transfected into another breast cancer cell line (MCF-7), with or without ERα, GATA-2 or GATA-3." (PMID 27105516, 2016).
neutropenia (21 papers, 2012 to 2025). A decrease in the number of neutrophils found in the blood. "Although thrombocytopenia has been noted in individuals with GATA2 deficiency, it is typically within the context of other cytopenias, most commonly neutropenia." (PMID 40148527, 2025). "Inherited bone marrow failure syndromes (IBMFSs) include Fanconi anemia, Diamond–Blackfan anemia, Shwachman–Diamond syndrome, dyskeratosis congenita, severe congenital neutropenia, and other rare entities such as GATA2 deficiency and SAMD9/9L mutations." (PMID 37627314, 2023). "Whole-Exome Sequencing revealed a mutation in GATA2 causes a rare Syndromic Congenital Neutropenia With Intellectual Disability." (PMID 35436926, 2022). "The enhancer deletion in gata2aΔi4/Δi4 mutants leads to a hypocellular WKM and neutropenia, strongly suggestive of marrow failure, a hallmark of disease progression in Gata2 deficiency syndromes." (PMID 32054973, 2020). "Since then, a high incidence of GATA2 variants has been found in patients with mild neutropenia who evolve to develop MDS and AML." (PMID 32066420, 2020). "Despite the early rescue, gata2aΔi4/Δi4 adults showed increased susceptibility to infections, oedema, a hypocellular WKM and neutropenia, a phenotype resembling key features of GATA2 deficiency syndromes in humans." (PMID 32054973, 2020). "GATA2 deficiency results in a range of haematological abnormalities, including neutropenia." (PMID 40822568, 2024). "The remaining 10 patients have JAGN1 deficiency (n = 1); poikiloderma with neutropenia (n = 1); cystic fibrosis (n = 1); leukocyte adhesion deficiency type 3 (n = 1); GATA2 deficiency (n = 1); undefined leukopenia (n = 1); and unspecified phagocytic diseases (n = 4)." (PMID 37559153, 2023). "All patients with GATA2 deficiency presented in this retrospective cohort had neutropenia." (PMID 35273927, 2022). "In addition to these findings, we have studied two patients with GATA2 mutations who presented WS-like features (Mycobacterium avium infection, Warts and Neutropenia) together with an impaired CXCR4 internalization." (PMID 23009155, 2012). "Depending on the causative genetic lesion, neutropenia can sometimes present with extra-haematopoietic abnormalities such as pancreatic exocrine insufficiency (SBDS, ELF1) and deafness (GATA2)." (PMID 32066420, 2020). "In this region, several candidate genes (GATA2, PPARG, RAF1 and SEC61A1) associated with functions such as quantity of leukocytes or neutropenia were identified." (PMID 33116177, 2020). "This suggests some eventual interplay between CXCR4-dependant signalling and GATA2 that could account for the manifestations of neutropenia and warts of the GATA2 syndrome and beyond, of the more recently described Serine threonine kinase 4 (STK4)-linked syndrome." (PMID 23009155, 2012).
anemia (19 papers, 2007 to 2026). A reduction in the number of red blood cells, the amount of hemoglobin, and/or the volume of packed red blood cells. "Underlying this anemia was abnormal expression of both GATA2 and PU.1, transcription factors critical for cell fate decisions during hematopoiesis.." (PMID 35330735, 2022). "The VECre mediated Gata2 loss resulted in death from anemia, hemorrhage, and edema due to lymphatic dysfunction." (PMID 34387894, 2021). "We established a Gata2-L359V knockin mouse model in which the homozygous Gata2-L359V mutation caused major defects in primitive erythropoiesis with an accumulation of erythroid precursors and severe anemia, leading to embryonic lethality around E11.5." (PMID 34078881, 2021). "GATA2 c.1061 C > T; p.T354 M mutation was identified after he progressed from myelodysplastic pancytopenia to refractory anemia with excess blasts type II." (PMID 31035956, 2019). "A GATA2-deficient mouse exhibited severe anemia and died at early stage of gestation due to a reduced number of primitive erythroid cells and HPCs, highlighting the essential role of GATA2 in early hematopoiesis." (PMID 26246892, 2015). "Gata2 is indispensable for hematopoiesis, with knockout mice typically exhibiting embryonic lethality attributed to severe anemia and defective hematopoietic stem cell (HSC) development." (PMID 42253983, 2026). "Germline mutations in other transcription factors, including GATA2, and RUNX1 can also contribute to inherited anemias." (PMID 35330735, 2022). "The downregulation of Gata2 induced by gene KO or the deletion of a cis-regulatory element of Gata2 resulted in embryonic lethality with severe anemia at E10.510,58." (PMID 34078881, 2021). "In response to anemia, one mechanism of stress resolution involves the GATA2-regulated activation of the Samd14–Enh intronic enhancer." (PMID 32241909, 2020). "Samd14–Enh is one of a cohort of GATA2 and anemia-activated enhancers predicted to regulate stress-dependent transcription in erythroid progenitors." (PMID 32241909, 2020). "Gata2 knockout embryos die by 11.5 dpc due to severe anemia, and cells from their YS and AGM regions exhibit relatively low hematopoietic potential, as assessed by colony formation." (PMID 26389592, 2015). "Similar to the Actb−/− embryos in this study, Gata2 knockout embryos show marked anemia and fail to survive beyond the stage of primitive hematopoiesis." (PMID 23840778, 2013). "GATA2 null mice areembryonic lethal, due to severe anemia during the early phase of YS hematopoiesis(E10-11)." (PMID 24324557, 2013). "Gata2 is mainly expressed in the HSCs and progenitor cells and regulates the hematopoietic process, and the deletion of Gata2 in mice leads to defects in the hematopoietic process resulting in severe anemia and death." (PMID 33193725, 2020). "Gata2 and Samd14 transcription are both controlled by enhancers harboring a nearly-identical conserved E-box spacer–GATA composite element, and the study of these and related enhancers established a GATA2 and anemia-activated genetic network with many potentially-critical network constituents." (PMID 32241909, 2020). "The depletion of GATA2 results in embryonic lethality at E11.5, in part due to anemia." (PMID 31281375, 2019). "Gata2 levels were found to be similarly decreased at days 1 and 4 in both groups, but while levels recovered to normal values in the light anemia group at day 7, they were kept down-regulated in the severe anemia group until the end of the experiment." (PMID 27100629, 2016). "Our results regarding the observed decrease in primitive hematopoiesis in the Actb−/− embryo are consistent with the observed anemia and lethality at E10.5 in Gata2 knockout embryos indicating that the diminished expression of Gata2 contributes to this phenotype in the Actb−/− embryos." (PMID 23840778, 2013).
anemia (continued). "The transcription factor GATA-2, which is expressed during the earliest stages of hematopoiesis, is essential for early hematopoietic development; GATA-2-/- mice have severe anemia and are deficient in the proliferation and survival of multipotent hematopoietic progenitors." (PMID 17708765, 2007). "GATA2 is required for both pro-definitive and definitive hematopoiesis, and mutant mouse embryos lacking GATA2 die before E11.5 due to severe anemia." (PMID 33783643, 2021). "Before the discovery of GATA2 as a disease gene in humans, the first Gata2 knockout (KO‐Gata2−/−) mice generated showed embryonic lethality at 10.5 days post coitum due to lack of definitive hematopoiesis and severe anemia." (PMID 34387894, 2021). "We found that PDS increased the proportion of both hematopoietic stem cells and erythroid progenitor cells in the bone marrow, but PPD inhibited spleen erythroid differentiation and reduced the expression of GATA-1 and GATA-2 and could not improve tumor-induced anemia in mice." (PMID 32015754, 2020).
bone marrow failure (19 papers, 2016 to 2026). "Germline GATA2 deficiency predisposes to bone marrow failure, myeloid neoplasia, and immune dysregulation." (PMID 42130790, 2026). "As insufficient GM-CSF signaling caused pulmonary alveolar proteinosis and excessive IL-6 signaling promoted bone marrow failure and GATA2 deficiency patient phenotypes, these results provide insight into mechanisms underlying GATA2-linked pathologies." (PMID 36809258, 2023). "The most frequent germline syndromes are caused by pathogenic variants in transcription factors like CEBPA, ETV6, GATA2, and RUNX1, in the RNA helicase DDX41, and a variety of genes associated with telomere biology disorders and inherited bone marrow failure." (PMID 37904876, 2023). "Most patients with GATA2-deficiency have been diagnosed with MDS, CMML/juvenile myelomonocytic leukemia, MDS/MPN overlap, AML and bone marrow failure (78.3%, n=508)." (PMID 37904876, 2023). "In children and adolescents, OS and disease-free survival (DFS) after HSCT in bone marrow failure, MDS, or AML in patients with GATA2 deficiency were 65% and 51%, and those were comparable to the values in patients without GATA2 deficiency." (PMID 36185231, 2022).
COVID-19 (19 papers, 2021 to 2026). A disease caused by infection with severe acute respiratory syndrome coronavirus 2. "Here, we describe a young adult with GATA2 deficiency presenting with Legionella pneumonia, COVID-19, and HLH with underlying SF3B1-mutated myelodysplasia that responded successfully to allogeneic hematopoietic stem cell transplantation." (PMID 42130790, 2026). "Transcription factor GATA2 is associated with hematopoietic dysfunction in severe COVID-19 patients." (PMID 38162574, 2023). "Severe acute respiratory syndrome coronavirus 2 (SARS-CoV-2) infection has been reported to impair immune function, but its effects on GATA2 mutation carriers remain unclear." (PMID 40797383, 2025). "The identified TFs, such as FOXC1, GATA2, YY1, FOXL1, FOXO3, STAT1 and STAT3, are associated with COVID-19." (PMID 37261353, 2023). "in a study identified YY1, CREB1, and GATA2 to be critical TFs involved in the regulation of COVID-19 patients at the genetic level in their pathogenesis." (PMID 37283761, 2023). "HSPCs differentiation-related genes, such as GATA1 and GATA2, were significantly downregulated in the COVID-19 group." (PMID 37446049, 2023). "Collectively, MkP- and GP-priming TFs, including ETS2, FLI1, SPI1, and GATA2 were activated in the HSC/MPP cells from COVID-19 patients, probably contributing to the increased output of myeloid progenitor cells and decreased output of lymphoid progenitors." (PMID 34349096, 2021). "Interestingly, we found that GATA2 expression and promoter chromatin accessibility were significantly reduced in the STs of the patients with COVID-19." (PMID 37400500, 2023). "A recent study about the genomics of COVID-19 showed that TFs like FOXC1, GATA2, YY1, FOXL1, and NFKB1 regulated the inflammatory network in SARS-CoV-2 infections." (PMID 35747501, 2022). "Consistently, the regulons including GATA2, SPI1, ETS2, FLI1, and ETV6 were activated in COVID-19 patients." (PMID 34349096, 2021). "The rs21075238 is located at the binding site for GATA binding protein 2 (GATA2), which is involved in the transcriptional regulation of proinflammatory cytokines therefore, CCL5 might participate in the COVID-19 inflammatory process." (PMID 40881695, 2025). "In our analysis, FOXC1, GATA2, YY1, and PPARG may play a role in the development of COVID-19 and IS." (PMID 37184686, 2023). "FOXC1, YY1, GATA2, FOXL, STAT1 and STAT3 are important TFs for COVID-19." (PMID 37261353, 2023). "Furthermore, our research indicates that transcription factors FOXC1, GATA2, YY1, NR2C2, and E2F4 were overexpressed in common DEGs of psychiatric disorders and COVID-19." (PMID 35185890, 2022). "Up-regulation of ETS2, FLI1, GATA2, and ETV6 in the HSC/MPPs of COVID-19 patients raised the speculation that the HSC/MPPs preferentially differentiated into MkP cells." (PMID 34349096, 2021). "In comparison, the scores of GATA2 significantly increased only in HSC/MPPs from patients with severe COVID-19, rather than in those from mild cases when compared with HC." (PMID 34349096, 2021).
neuroblastoma (19 papers, 2009 to 2025). Neuroblastoma (NB) is the most common solid, extracranial childhood tumor. "Fate 2, corresponding to cluster cIVS, exhibited increasing expression of neuronal function markers NPY, MAP2, GAP43, and GATA2, which are associated with differentiating neuroblastomas." (PMID 40448172, 2025). "Neuroblastoma-associated super-enhancers are distributed among a broad range of genomic loci of human GATA2 and GATA3." (PMID 33803938, 2021). "Accordingly, GATA-2 overexpression has been shown to cause differentiation of human neuroblastoma SK-N-BE2 cells." (PMID 19707195, 2009). "In an attempt to select genes for prognosis prediction in neuroblastoma, among other genes GATA-2 has been observed to be associated with favourable prognosis, which is strengthened by our detailed analysis." (PMID 19707195, 2009). "GATA2 has been identified as a component of the transcriptional regulatory circuits involving super enhancers in neuroblastoma cells, which also includes GATA3, PHOX2A, PHOX2B, and HAND2." (PMID 36980710, 2023). "The cRE1–3 overlaps with regions of chromatin open only in neuroblastoma cell lines, where GATA2 is also transcribed." (PMID 37386251, 2023). "A study in neuroblastoma suggests that GATA2 plays a role in ATRA-induced neuronal differentiation in neuroblastoma SH-SY5Y cells." (PMID 36980710, 2023). "GATA2 was significantly increased in carcinomas and neuroblastomas compared to respective normal cells." (PMID 35326649, 2022). "Transcription factor GATA2 has been shown to be involved in tumorigenesis in multiple human tumors, such as the chronic myelogenous leukemia and neuroblastoma." (PMID 31088566, 2019). "These CpGs are situated in the potential promoter/5’UTR region, which in neuroblastoma cells binds GATA-2, a hematopoietic transcription factor that regulates proliferation of blood cell lineages." (PMID 27171005, 2016). "GATA2 is a transcription factor necessary for normal hematopoietic and neural development, and is often specifically and highly expressed in neuroblastoma." (PMID 24147068, 2013). "Other implications of GATA2 are seen in the neuroblastoma: GATA2, essential for normal SNS development, is downregulated in aggressive neuroblastoma." (PMID 22676581, 2012). "As northern blot results suggested differential GATA-2 and -3 expression in different clinical neuroblastoma subgroups, we also analysed their associations with tumour characteristics." (PMID 19707195, 2009). "The expression levels of GATA-2 and -3 were also higher in the more favourable subtypes of neuroblastoma." (PMID 19707195, 2009). "To evaluate these observations, we used microarray data of 251 primary neuroblastomas, and compared the expression levels of GATA-2, -3, -4 and FOG-2 in different clinico-genetic subgroups." (PMID 19707195, 2009). "Localised neuroblastoma had higher GATA-2 and -3 expression levels than tumours of stage 4 (P=0.048) and 5F (P=0.039))." (PMID 19707195, 2009). "Next, we overexpressed GATA2 plasmid DNA in the two neuroblastoma cell lines and measured cell viability in response to #5333 and #5338 treatment but were unable to show a reduced drug effect on cell viability in the presence of excess GATA2." (PMID 36980710, 2023). "GATA2 repression by siRNA increased the sensitivity of neuroblastoma cells to the two compounds, suggesting that GATA2 could be the downstream target in mediating the anti-cancer effects of #5333 and #5338." (PMID 36980710, 2023). "Considering that GATA2 also participates in sympathoadrenal development, it would be important to elucidate whether GATA2 plays a role in the genesis and maintenance of neuroblastoma, as does GATA3, under similar regulatory mechanisms." (PMID 33803938, 2021). "Although FOG-2 is likely to interact with any GATA protein, our data obtained in neuroblastoma specimens suggest a predominant interaction with GATA-2 and/or GATA-3; in addition, the interaction between FOG-2 and GATA-4 could be disturbed." (PMID 19707195, 2009).